MIR6770-1 (microRNA 6770-1)
Synonyms: hsa-mir-6770-1
Gene: MicroRNA gene on chromosome 16 (14,930,820 to 14,930,879, forward strand). Ensembl gene ENSG00000278265.
Homologues: Paralogues in human: MIR6770-2 (100% identical), MIR6770-3 (100% identical).